LEUTX (leucine twenty homeobox)
Description:
[Isoform 1]: Paired-like homeobox transcription factor involved in embryogenesis. May act as a regulator of embryo genome activation. Binds to a 36 bp DNA elements containing a 5'-TAATCC-3' sequence motif, referred to as EEA motif (EGA-enriched Alu-motif), present in the promoters of target genes activated in early embryos. [Isoform 2]: Inactive transcriptional activity.
Tractability: No criterion of Open Targets' tractability assessment is met for any kind of drug.
Gene: Protein-coding gene on chromosome 19 (39,776,595 to 39,786,291, forward strand). Ensembl gene ENSG00000213921.
Subcellular location: Nucleus
Subcellular location (Human Protein Atlas): Nucleoli; Nucleoplasm
Pathways (Reactome):
Developmental Biology: Zygotic genome activation (ZGA)
Gene Ontology:
Molecular function: protein binding; DNA-binding transcription factor activity, RNA polymerase II-specific; RNA polymerase II cis-regulatory region sequence-specific DNA binding; DNA binding
Biological process: regulation of transcription by RNA polymerase II; regulation of DNA-templated transcription
Cellular component: nucleus; chromatin; nucleoplasm
Genetic constraint (gnomAD): Loss-of-function variants: 3 observed, 3.18 expected, observed/expected ratio (o/e) 0.94, 90% interval 0.41 to 1.84. That is too few expected variants to judge how well the gene tolerates losing a copy. Missense variants: 207 observed, 218.02 expected, observed/expected ratio (o/e) 0.95, 90% interval 0.85 to 1.07. Synonymous variants: 75 observed, 77.66 expected, observed/expected ratio (o/e) 0.97, 90% interval 0.8 to 1.17.
Homologues: Orthologues: chimpanzee LEUTX (99% identical), macaque LEUTX (73% identical). Paralogues in human: DBX1 (21% identical), DBX2 (19% identical), HLX (18% identical).
Diseases named in the same sentence as LEUTX in open-access papers:
LEUTX is named in the same sentence as 19 diseases in open-access papers, as found by Europe PMC text mining. Sharing a sentence is not in itself a finding about the gene and the disease. The quoted sentences say what the papers report.
sarcoma (7 papers, 2019 to 2024). A usually aggressive malignant neoplasm of the soft tissue or bone. "The elevated expression of LEUTX seen in these tumors is in line with a prior study that reported a BRD4::LEUTX fusion in a pediatric sarcoma." (PMID 38500181, 2024). "These three cases were CIC::LEUTX fused CNS tumors which clustered to MC CIC-rearranged sarcoma in methylation profiling, Their morphology was also similar to that of peripheral CIC sarcoma." (PMID 38926750, 2024). "While much less is known about the clinical features associated with CIC::LEUTX sarcoma, a recent study that profiled pediatric CNS tumors identified 9 patients with CIC::LEUTX fusions that all occurred within the supratentorial compartment." (PMID 38882060, 2024). "In this multicenter study, we describe a cohort of tumors with CIC fusions, including 14 CNS cases (containing 6 CIC::LEUTX fusion tumors) and 5 peripheral sarcoma cases, with a particular focus on those with rare fusion partners and their diverse clinical outcomes." (PMID 38926750, 2024). "In our study of 19 tumors featuring CIC fusions, spanning both CNS and peripheral tissues, we observed that only CNS tumors harboring the CIC::LEUTX fusion exhibited neuroepithelial differentiation with better outcomes compared to those of CIC-rearranged sarcomas." (PMID 38926750, 2024). "Whereas CIC::LEUTX and CIC::NUTM1 have also been reported in a subset of CIC-rearranged sarcomas, fusions implicating the ATXN1 gene seem to be only encountered in CNS tumors." (PMID 36737790, 2023). "These occur across a spectrum including conventional CIC-altered sarcoma, high-grade neuroepithelial tumor, and even rare lower-grade glial tumors, indicating that not all the intracranial CIC-fused tumors are CIC-altered sarcomas, especially those with CIC::LEUTX genetic fusion." (PMID 38926750, 2024).
CNS embryonal tumor (4 papers, 2023 to 2025). "A third case was found in a series of medulloblastoma, where re-evaluation using version 12 of the Heidelberg classifier showed a match to CNS embryonal tumor with BRD4::LEUTX fusion." (PMID 38500181, 2024). "One of these reports characterized the fusion in a large series of pediatric cancers, while the other incorporated detailed clinical and pathological data, including methylome analysis matching to the novel Heidelberg version 12 classifier class “CNS embryonal tumor with BRD4::LEUTX fusion”." (PMID 38500181, 2024). "Finally, using the Heidelberg DNA-methylation classifier, the case was classified as “CNS Embryonal Tumor with BRD4:LEUTX Fusion” (with a calibrated score (cs) of 0.99)." (PMID 36934287, 2023). "Published patient case reports have identified the CIC::LEUTX chimera to occur between CIC exon 20 and LEUTX exon 3 across the different cancers of renal sarcoma, spinal cord sarcoma, angiosarcoma, central nervous system embryonal tumors, and pediatric-type high-grade neuroepithelial tumors." (PMID 38882060, 2024). "Here, we report a pediatric case of a novel tumor type among the other CNS embryonal tumors classified within the methylation class (MC) “CNS Embryonal Tumor with BRD4:LEUTX Fusion” (calibrated score (cs): 0.99) which is not yet integrated into the CNS WHO classification." (PMID 36934287, 2023).
embryonal tumors (3 papers, 2020 to 2024). "Recent research has linked gene fusions involving LEUTX to oncogenesis, particularly in primary CNS sarcomas and high-grade neuroepithelial tumors that harbor CIC::LEUTX fusions, as well as in embryonal tumors with BRD::LEUTX fusions." (PMID 38926750, 2024). "Recently, two cases of CNS embryonal tumors harboring a BRD4::LEUTX fusion were described." (PMID 38500181, 2024). "Embryonal tumors with multilayered rosettes (ETMRs) which otherwise lack rosettes, a medulloepithelioma component, and neurocytic/neuropil-rich areas could also resemble embryonal tumors with BRD4::LEUTX fusions, but they are generally negative for OLIG2 and positive for LIN28A." (PMID 38500181, 2024).
neuroepithelial tumors (3 papers, 2023 to 2024). "Notably, within our cohort, we discovered two cases of neuroepithelial tumors with CIC::LEUTX fusion that demonstrated prolonged progression-free survival (PFS) and presented with unique, unassigned methylation signatures." (PMID 38926750, 2024).
CNS sarcomas (2 papers, 2024). "Fusions in this gene also play a role in cancer, including in primary CNS sarcomas involving CIC::LEUTX fusions, and of interest, CIC::LEUTX fusions have recently been described in a novel glioneuronal tumor." (PMID 38500181, 2024).
medulloblastoma (2 papers, 2024 to 2025). A malignant, invasive embryonal neoplasm arising from the cerebellum. "Inspection of methylation signatures using UMAP for the four NIH cases and 2 of the previously published cases fore which (IDAT) files were available showed that CNS tumors with BRD4::LEUTX fusion cluster together, near but separate from group 3 medulloblastoma." (PMID 38500181, 2024). "A fourth case was included as a low-score match to group 3 medulloblastoma in the initial paper describing the Heidelberg version 11 methylation classifier, but which in our analysis of the Heidelberg version 12 classifier, matched to CNS embryonal tumor with BRD4::LEUTX fusion." (PMID 38500181, 2024).
neuroblastoma (1 paper, 2024). Neuroblastoma (NB) is the most common solid, extracranial childhood tumor. "Indeed, pathological features can overlap between embryonal tumor subtypes, particularly those with BRD4::LEUTX fusions and FOXR2-activated neuroblastomas; most notably the small poorly differentiated cells, abundant necrosis, and co-expression of immunomarkers synaptophysin and OLIG2." (PMID 38500181, 2024).
tumor (7 papers, 2020 to 2025). "In this study, we find that CNS embryonal tumor with BRD4::LEUTX fusion is a provisional tumor type occurring in young children." (PMID 38500181, 2024). "In all 3 cases, expression of BRD4, and especially that of LEUTX was high relative to expression of these genes in the broad dataset of tumor types." (PMID 38500181, 2024). "One case presented a dedicated case report for a tumor matching to the methylation class “CNS embryonal tumor with BRD4::LEUTX fusion”, with demonstration of the fusion." (PMID 38500181, 2024). "We demonstrate that CNS embryonal tumor with BRD4::LEUTX fusion comprises a well-defined methylation class/cluster." (PMID 38500181, 2024). "The Heidelberg DNA-methylation classifier classified this case as “CNS Embryonal Tumor with BRD4:LEUTX Fusion”." (PMID 36934287, 2023). "In addition to these 5 cases, we describe 4 additional unpublished new cases of CNS tumors with BRD4::LEUTX fusions, thereby expanding the limited characterization available for this tumor type to date." (PMID 38500181, 2024). "We report on a series of cases that show fusions involving BRD4 and LEUTX and match to the corresponding DKFZ-Heidelberg class describing this tumor type." (PMID 38500181, 2024). "Gene expression was available for 3 of the 4 cases profiled at the NIH, where the expression of LEUTX and BRD4 was compared to the clinical dataset of > 2700 samples of a variety of tumor types with gene expression data available." (PMID 38500181, 2024). "DNA and/or RNA sequencing revealed recurrent fusions involving the capicua transcriptional repressor (CIC) gene in 10/10 tumor samples analyzed, with the most common fusion being CIC::LEUTX (n = 9)." (PMID 36964296, 2023). "One proposed tumor type, CNS tumor with BRD4::LEUTX fusion, has been described." (PMID 38500181, 2024).
CNS tumors (5 papers, 2023 to 2024). "Their analysis revealed that CIC::LEUTX bearing CNS tumors segregated into its own group characterized by a pediatric-type high-grade neuroepithelial histology that was distinct from the CIC-rearranged CNS sarcoma group." (PMID 38882060, 2024). "Our study reveals that pediatric CNS tumors harboring the CIC::LEUTX fusion represent a heterogeneous set of tumors." (PMID 38926750, 2024). "As only a few CNS tumors with BRD4::LEUTX fusions have been described, we herein characterize a cohort of 9 such cases (4 new, 5 previously published) to further describe their clinicopathologic and molecular features." (PMID 38500181, 2024). "In our series, 10 out of 12 CNS tumors showed gene locus aberrations related to their fusion partners, particularly those with LEUTX, where all six cases demonstrated LEUTX locus aberrations." (PMID 38926750, 2024). "Notably, three of the six CNS tumors with CIC::LEUTX fusions clustered elsewhere: Case 1 clustered to the reference set “HGNET CIC fusion-positive”." (PMID 38926750, 2024). "In all six primary CNS tumors featuring CIC::LEUTX gene fusions, methylation array-based copy number profiling consistently revealed LEUTX locus aberrations at chromosome 19q13.2, demonstrated by visual inspection of LEUTX locus loss or gain (6/6, 100%) in CNV results." (PMID 38926750, 2024). "This novel group of tumors, epigenetically distinct from all known CNS neoplasms, shows recurrent gene fusions involving the transcriptional repressor CIC (most commonly with LEUTX) as an additional unifying feature." (PMID 36964296, 2023).
cancer (4 papers, 2016 to 2024). A tumor composed of atypical neoplastic, often pleomorphic cells that invade other tissues. "A second case had been discovered in a large series of pediatric cancers where the BRD4::LEUTX fusion had been identified in one case of the series." (PMID 38500181, 2024). "We then assessed LEUTX expression in the publicly available data on 675 human cancer cell lines." (PMID 27578796, 2016). "We found that even with differences in cell lines, batch effects, and other experimental differences LEUTX ChIP-Seq peaks were often proximal with known EP300 binding sites particularly in H1 cell line data, in comparison to cancer cell lines." (PMID 36876139, 2023).
LEUTX also shares sentences with these, for which no sentence is quoted: angiosarcoma (2 papers); alveolar rhabdomyosarcoma (1); Facioscapulohumeral dystrophy (1); glial tumors (1); glioneuronal tumor (1); renal sarcoma (1); retinoblastoma (1); spinal cord sarcoma (1); undifferentiated sarcoma (1).